IL33 (interleukin 33)
Diseases named in the same sentence as IL33 in open-access papers (continued):
Sharing a sentence is not in itself a finding about the gene and the disease.
tumor (continued). "Notable decreased cytokines in the KEAP1-KO clones included IL-7R alpha, IL-18, IL-23, IL-31, and IL-33, which are pro-inflammatory and correlate with infiltration and activation of T cells and anti-tumor responses." (PMID 38542481, 2024). "In conclusion, IL-33 supports tumour growth and influences immune surveillance in the tumour microenvironment, favouring immune escape of tumour cells." (PMID 38662248, 2024). "The analysis of the main molecules that regulate EMT, namely E-Cadherin and N-Cadherin denoted a reversion of this process in mouse and human tumor cells following exposure to IL-33 activated eosinophil-derived EV." (PMID 39061080, 2024). "It is now clear that IL-33 and cancer cell interactions within the tumour microenvironment regulate cancer stem cell properties and play an important role in tumour progression and metastasis." (PMID 38662248, 2024). "We initially corroborated a substantial reduction in both the proportion and absolute count of ILC2s within the spleens of IL-33−/− tumor-bearing mice, in stark contrast to their wild-type tumor-bearing counterparts." (PMID 38430390, 2024). "Conversely, IL-33 contributes to intestinal polyposis and tumorigenesis through immune and wound-healing responses mediated by tumor epithelial cells." (PMID 39309440, 2024). "Meanwhile, we observed a significant decline in the frequency and quantity of ILC2s within the tumor tissues of IL-33−/− tumor-bearing mice, in comparison to WT tumor-bearing mice." (PMID 38430390, 2024). "Previous studies observed that cisplatin treatment induces NRF2-mediated antioxidant response in tumor-initiating cells to trigger the extracellular release of the ‘danger’ signal IL-33." (PMID 38778059, 2024). "Identified as a potent stimulator of immune responses and a contributor to wound healing, the complex role of IL-33 in modulating the Tumor Microenvironment (TME) is increasingly attracting attention." (PMID 37762328, 2023). "Conversely, endogenous IL-33 in the tumor microenvironment has been postulated to inhibit NF-κB expression, hence reducing the induction of “fragile” Foxp3+ Tregs and promoting the production of IFN-γ." (PMID 37686309, 2023). "PDGF-BB mediated the infiltration of M2-phenotype tumor-associated macrophages (TAM) into tumor tissue by inducing pericyte- and fibroblast-derived IL-33 in a mouse tumor xenograft model." (PMID 38193080, 2023). "In IL-33-treated TB mice, the cDC1 population increased significantly only in the spleen but decreased or remained unchanged in the tumor mass and tumor-draining lymph nodes (tdLNs)." (PMID 37246159, 2023). "Taking these results together, we suggest that the enhanced antitumor immunity and tumor growth inhibition seen in IL-33-treated TB mice are due to a newly developed immunogenic population of CD103+ cDC1s in the spleen." (PMID 37246159, 2023). "In the tumor environment, the IL-33/ST2 axis was reported to promote Treg expansion and to alter the immune system in tumor-promoting ways." (PMID 37246159, 2023). "In the context of cancer, the IL-33/ST2 signaling pathway influences the tumor microenvironment by activating immune effector cells and regulating the recruitment of pro- or anti-tumorigenic cells." (PMID 37762328, 2023). "This work was initiated with a finding that the cDC1 population increased significantly only in the spleens of IL-33-treated TB mice in which tumor growth was profoundly suppressed." (PMID 37246159, 2023). "Among cytokines, βA most significantly increased the expression of Il1b, Il18 Il33, and Il15, both within tumor cells and fibroblasts." (PMID 38304252, 2023). "IL-33-activated eosinophils inhibited tumor growth via degranulation and cytolytic cytokine secretion in syngeneic and metastatic tumor models." (PMID 37246159, 2023). "Twenty-two studies investigated the relationship between IL-33 tissue levels and tumor clinicopathological parameters." (PMID 37507682, 2023).
tumor (continued). "The clinical and biological significance of IL-33, including its effects on both T cells and tumor cells, as well as its relationship with 5-FU chemotherapeutic activity were examined in ex vivo, in vitro and in vivo models of CRC." (PMID 37056569, 2023). "In mice, IL-33-activated ILC2 cells enhanced anti-tumor immunity in a model for primary and metastatic lung tumor." (PMID 37781372, 2023). "IL-11, which is derived from tumor cells, is a crucial factor involved in inducing IL-33 production in gastric cancer cells." (PMID 37686309, 2023). "IL-33 (a member of IL-1 cytokine family) also promotes tumor survival and progression through different mechanisms, including Tregs functional stabilization." (PMID 37275901, 2023). "Mechanistically, IL-33-mediated T cell responses led to the activation of tumor cell-intrinsic apoptotic and immune killing-related signals, thereby enhancing the sensitivity of CRC cells to 5-FU." (PMID 37056569, 2023). "In the Abcam group, IL-33 expression was positively correlated with tumor stage and negatively correlated with histological grade but not with tumor size or lymphatic invasion." (PMID 37507682, 2023). "FL-BMDCs generated in the presence of IL-33 (FL-33-DCs) offered more potent tumor immunotherapy than control Flt3L-BMDCs (FL-DCs)." (PMID 37246159, 2023). "Compared with healthy cecum, the orthotopic cecal wall tumor model has ST2+ TAMs (tumor-associated macrophages) that, under the influence of IL-33, limit M2 polarization and the cytotoxic activity of CD8+ T cells." (PMID 37686309, 2023). "In the Sigma group, only tumor size was positively correlated with IL-33 expression (OR = 1.878, 95% CI = 1.367–2.581, p < 0.000)." (PMID 37507682, 2023). "IL-33 production upregulates PD-1 and/or PD-L1 in tumor cells as well as T cells, NK cells, and ILC2 cells." (PMID 37587450, 2023). "In this study, we first demonstrated that IL-33 expressed by tumor cells was a dominant mediator of antitumoral immunity in 5-FU-sensitive patients." (PMID 37056569, 2023). "The IL-33/ST2 axis affects tumor growth by regulating mitophagy in macrophages and reprogramming their polarization." (PMID 37719702, 2023). "However, when Treg cells lack IL-33, the tumor microenvironment changes, causing the cells to transform into “fragile” Treg cells with considerably increased PD-1 expression, lower neuropilin-1 (Nrp-1) expression, and loss of IL-33’s inhibitory effect on NF-κB." (PMID 37686309, 2023). "Also, IL-33, a pleiotropic cytokine, is closely associated with cancer such as colorectal cancer and myeloproliferative neoplasms, which may be related to mast cells and tumor microenvironment(TME)." (PMID 37153553, 2023). "Specifically, the high expression of IL-33 will increase the likelihood of cancer histologic grade differentiation, tumor stage, increased distant metastasis, and larger tumor size." (PMID 37507682, 2023). "In the Proteintech group, IL-33 expression was positively correlated with tumor stage (OR = 3.206, 95% CI = 1.511–6.802, p = 0.002)." (PMID 37507682, 2023). "This in turn resulted in the secretion of IL-33, resulting in a pro-type 2 immune response and tumor progression in this PDAC subset." (PMID 37910468, 2023). "On the other hand, during CRC progression, the abnormal expression of IL-33 in the TME activates tumor stroma to promote intestinal polyposis." (PMID 36766801, 2023). "Both anti-fungal treatment or IL-33 suppression decreased TH2 infiltration and caused tumor regression." (PMID 37901238, 2023). "The IL-33-mediated optimal immunometabolic reprogramming in ILC2s also requires ROS, and its inhibition can prevent its tumor-promoting role by suppressing IL-5 and IL-13 release." (PMID 37275901, 2023). "In contrast, treatment of tumor‐bearing mice with recombinant IL‐33 and ICI in vivo led to induction of eosinophils and subsequent activation of CD8+ T cells and resulted in improved tumor control and survival prolongation." (PMID 36892326, 2023).
tumor (continued). "Together, these results indicate that IL-33-mediated T cell responses drive both tumor cell-intrinsic apoptotic and immune killing-related signals in CRC cells." (PMID 37056569, 2023). "Treatment with IL-33 also drives the cytotoxic activities of Tc9 cells induced by DCs thereby promoting the therapeutic efficiency of tumor vaccines based on DCs." (PMID 37153553, 2023). "There is a positive correlation reported between human CRC development and IL-33/IL-1RL1 expression levels, which reduces tumor growth in skin cancer and CRC models." (PMID 37176567, 2023). "IL-33 overexpression was positively correlated with tumor stage, histological grade, distant metastasis and tumor size, and the expression of IL-33 was correlated with a low 5-year OS rate and 3-year OS rate in cancer patients." (PMID 37507682, 2023). "We also explored the clinical and biological significance of IL-33, described its dual effects on both T cells and tumor cells, and highlighted its bias toward an antitumoral T cell-based axis in the TME of CRC." (PMID 37056569, 2023). "More recent findings reveal a positive correlation between the overexpression of IL-33 and FOXP3 expression within the tumor microenvironment, suggesting that IL-33 contributes to immunosuppression." (PMID 37762328, 2023). "The released IL-33 recruited and induced type 2 immune cells into the tumor environment and facilitated PDAC development." (PMID 37868956, 2023). "The presence of FOXP3+ Tumor-Infiltrating Lymphocytes (TILs) has been associated with the tumor’s expression of IL-33, and intriguingly, the prognostic value of FOXP3 appears to be contingent upon the active expression of IL-33." (PMID 37762328, 2023). "In the meta-analysis section, at the tissue level, the overall analysis showed that the expression of IL-33 was positively correlated with tumor stage, histological grade, distant metastasis, and tumor size." (PMID 37507682, 2023). "In a study involving a mice model, intranasal administration of IL-33 reduced the number of lung metastasis by recruitment of eosinophils to the tumor site." (PMID 38090567, 2023). "Recent studies have shown that CAR-T cells armed with engineered interleukin-2 (IL-2) and interleukin-33 (IL-33) promote tumor control as a single-agent therapy." (PMID 38516299, 2023). "Eosinophils are a subset of granulocytes, and studies have shown that IL‐33‐activated eosinophils exert immediate cytotoxic effects on tumor cells." (PMID 35702880, 2023). "The results showed that the high expression of IL-33 was positively correlated with tumor stage, histological grade, distant metastasis, and tumor size." (PMID 37507682, 2023). "Intravenous injection of 4T1 tumor cells rendered NK cells recruited to the lungs through IL-33 stimulation, which depended on C-C motif chemokine ligand 5 (CCL5) expressed by eosinophils and CD8+ T cells." (PMID 37508545, 2023). "The majority of research implies that IL-33 promotes tumor migration, proliferation, and angiogenesis in gut cancer." (PMID 37686309, 2023). "Here, we explored how IL-33 orchestrates the T lymphocyte response to cancer by using transplant mouse tumor models." (PMID 37611111, 2023). "During tumor regression after PD1d/IL-2v/IL-33 ACT, OT1 TILs were mostly PD-1+ but highly enriched in TOXnegGzmc+ cells." (PMID 37081150, 2023). "A recent study found that although IL-33 mediated innate anti-tumor responses dependent on NK cell activity, IL-33 also activated ILC2s which in turn suppressed NK cell function, possibly through CD73 expression." (PMID 37514187, 2023). "IL-5-producing cells expand when treated with IL-25 and more so with IL-33 under Th2-skewing conditions, and IL-5 neutralization impairs eosinophil recruitment and increases tumor lung metastasis." (PMID 37587450, 2023). "The possibility of targeting the IL-33/ST2 axis in tumor immunotherapy, or as an adjuvant in immune checkpoint blockade therapy, is discussed." (PMID 37762328, 2023).
tumor (continued). "To verify the role of tumor cell-derived IL-33 in T cell responses, we constructed IL-33-overexpressing CRC cell lines and co-cultured these cells with T cells from PBMCs." (PMID 37056569, 2023). "In different types of tumors, the effect of IL-33/ST2 expression levels on tumor progression showed obvious inconsistencies." (PMID 37507682, 2023). "A correlation has also been observed in ESCC tissues between higher levels of IL-33 and increased density of stromal FoxP3+ Tregs, which are thought to enhance tumor progression attenuating the host immune response against ESCC." (PMID 37296602, 2023). "IL-33 created an immune-active tumor microenvironment by orchestrating antitumoral T cell responses." (PMID 37056569, 2023). "This MC phenotype correlates with the presence of high levels of Stem Cell Factor (SCF) and IL-33 inside the tumor." (PMID 37730723, 2023). "In gastric cancer, IL-33 secreted by tumor cells has been shown to activate mast cells and promote the expansion of tumor-associated macrophages (TAM)." (PMID 37256127, 2023). "In azoxymethane (AOM)/DSS-treated mice, the genetic blockade of the IL-33/ST2 pathway significantly prevents tumor formation with a reduction in intestinal tumor number, size, and grade compared with WT mice." (PMID 37296602, 2023). "IL-33 signaling has been found to alter the diversity, phenotype, and function of Tregs, potentially contributing to immune suppression and tumor progression." (PMID 37686309, 2023). "It has been suggested that the increased expression of IL33 in CAFs promotes tumor growth and metastasis via modulation of the immune system." (PMID 37954069, 2023). "Treatment of MC38 tumors with four rounds of IL-33 increased the accumulation of IL1RL1+ Treg cells in the tumor." (PMID 37611111, 2023). "Consistently, our findings showed that IL-33 promoted tumor cell proliferation and prevented chemotherapy-induced apoptosis in an autocrine manner." (PMID 37056569, 2023). "The Spearman correlation matrix showed that significant but weak correlations between VISTA H-score and PD-L1 H-score (tumor cells, p = 0.027; R = 0.263) or Il-33 H-score (tumor cells p = 0.04; R = 0.25) were found." (PMID 36836154, 2023). "Recently, tumor-specific Tc9 cells were reported in mice treated with IL-33-treated GM-CSF-induced BMDCs." (PMID 37246159, 2023). "The population of FCGR3+CD103+ cDC1s effectively induced antitumor immunity in IL-33-treated mice, leading to the inhibition of tumor progression." (PMID 37246159, 2023). "In patient samples acquired prior to Neoadjuvant Chemotherapy (NAC), the presence of both IL-33 and FOXP3 proteins was confirmed, with IL-33 detected primarily in the stromal tumor lesion." (PMID 37762328, 2023). "PPARγ is selectively expressed in group 2 innate lymphoid cells (ILC2s) supported the IL-33-dependent tumor promoting effect." (PMID 36816914, 2023). "In turn, IL-33-responding macrophages transmit paracrine TGF-β feedback signals to tumor cells, facilitating invasiveness and drug resistance and further up-regulating IL-33 expression." (PMID 36614179, 2023). "Building evidence shos that IL-33 plays a key role in several tumorigeneses by affecting tumor stem cells, tumor growth, metastasis, angiogenesis, and other many other tumorigenesis factors." (PMID 37507682, 2023). "Multiplex immunofluorescence staining revealed that ST2 was co-expressed with T cells and tumor cells, and that IL-33 was predominantly derived from tumor cells in the TME of CRC tissue." (PMID 37056569, 2023). "IL‐33, a tumour‐derived alarmin, in solid tumour induces eosinophil migration and promotes CCL11‐mediated eosinophil infiltration and degranulation, which in turn leads to tumour cell cytotoxicity and reduced tumour growth." (PMID 35344301, 2022). "It is also worth noting that IL-33 has an indirectly deleterious effect on NK cell function by metabolically modulating the tumor microenvironment." (PMID 35979357, 2022).
tumor (continued). "IL-33 induces the recruitment of M2-like macrophages to the tumor and stimulates macrophages to express M2 markers and produce matrix metalloproteinase-9, prostaglandin E2 and other molecules, both in vitro and in vivo." (PMID 36291105, 2022). "By contrast, expression of Il9 and Il4, known cytokine inducers of MMC and CTMC respectively, showed a marked IL-33 dependent increase in gp130F/F antral tumours, with levels in gp130F/FIl33−/−compound mutants comparable to those of WT controls." (PMID 35677533, 2022). "Roles of ILC2s, eosinophils and IL-33 in tumor immunity show contrasting results, which poses a difficulty in understanding the distinct roles of these players in deciding the fate of tumor cells." (PMID 35844571, 2022). "In cancer, the stimulation of ILC2s secreted by macrophages through IL‐33 induces the secretion of IL‐13 and IL‐5, which favour tumour progression." (PMID 35344301, 2022). "Tristetraprolin can effectively reduce IL-33 expression and tumor proliferation, metastasis, and escape in human GC cell lines and GC-bearing mice." (PMID 36291105, 2022). "Several reports on IL-33 have described a wide variety of effects attributed to tumor growth, such as increased cell adhesion, invasion, survival, and proliferation." (PMID 35409061, 2022). "Some studies have shown that a large number of hILC2s infiltrate and exert an anti-tumor effect in IL-33 enriched the tumor sites." (PMID 36246629, 2022). "The group of alarmins (HGMB1, IL‐1α, S100 proteins and IL‐33) showed a different role, promoting or inhibiting tumour progression, depending on the type of the tumour, stage and their localization." (PMID 35344301, 2022). "Recent findings have highlighted that ILC2s, together with IL-33 and eosinophils, participate in a considerably broad range of physiological roles such as anti-tumor immunity, metabolic regulation, and vascular disorders." (PMID 35844571, 2022). "In many cancers, IL-33 is a cancer promoting cytokine and boost Tregs to accumulate in peri-tumour areas." (PMID 35557940, 2022). "Genetic deficiency of IL-33 or antibody-mediated blockade of ST2 led to fewer tumours while transgenic overexpression of IL-33 specifically in intestinal epithelial cells via the villin promoter enhanced tumorigenesis in Apcmin/+ mice." (PMID 36263033, 2022). "As such, IL-33 appears capable of either promoting inflammation leading to tumorigenesis or altering anti-tumour immune responses, possibly depending on which immune cells receive IL-33/ST2 signaling." (PMID 35677533, 2022). "In the metastatic lymph node from human CRC patients, IL-33 expression is detected in CAF-like cells at areas of high desmoplasia at the tumour invasive front." (PMID 36263033, 2022). "IL-33 promotes tumour growth and proliferation in a COX-2 dependent manner, which is reversed upon ST2 blockade or COX-2 inhibition." (PMID 36263033, 2022). "IL-33 has many functions, for example in host immunity against tumor as an inhibitor, in angiogenesis as a promoter and can also induce tumor stroma remodeling." (PMID 35611243, 2022). "IL-33 induces CD40L expression by tumour infiltrating lymphocytes which promotes IFNγ+ production by NK cells and T cells." (PMID 36263033, 2022). "With the formation of tumor-promoting microenvironment and the activation of inhibitory immune cells, the antitumor effect of IL-33 is attenuated or even reversed." (PMID 35634336, 2022). "IL-33 is mainly secreted by endothelial and epithelial cells under stress conditions, and depending on the tumor microenvironment, it promotes or blocks tumor growth in murine models (Fournie & Poupot, 2018; J. X. Shen, Liu, & Zhang, 2018)." (PMID 35122833, 2022). "Many studies have reported that IL-33 upregulates programmed cell death protein 1 (PD-1) and/or PD-L1 in many tumor and immune cells, including as effector CD4+ T cells, CD8+ T cells, NK cells, and ILC2s." (PMID 36291105, 2022).